IL11RA (interleukin 11 receptor subunit alpha)
Diseases named in the same sentence as IL11RA in open-access papers (continued):
Sharing a sentence is not in itself a finding about the gene and the disease.
endometrial cancer (4 papers, 2010 to 2024). Primary or metastatic malignant neoplasm involving the endometrium (mucous membrane that lines the endometrial cavity). "Additionally, a study conducted by Lokau and colleagues found that antibodies targeting IL-11Rα in mice reduced overall tumour growth in endometrial cancer." (PMID 38248304, 2024). "We compared IL11, IL11Rα, pSTAT3 and SOCS3 protein in human endometrial carcinomas of varying histologic grades with endometrium from postmenopausal and cycling women." (PMID 20553623, 2010). "It indicates that IL11, along with its specific receptor, IL11Rα, and downstream signalling molecules, STAT3 and SOCS3, are likely to play a role in the progression of endometrial carcinoma." (PMID 20553623, 2010). "A recent study had identified that IL11 and IL11Rα are expressed in endometrial cancer, although there are no studies comparing the levels of IL11 protein in endometrial cancer and postmenopausal women in whom the vast majority of endometrial cancers develop." (PMID 20553623, 2010). "However, since endometrial cancer affects predominantly post-menopausal women, we compared the levels of IL11, IL11Rα, pSTAT3 and SOCS3 in endometrial cancer tissue to endometrial tissue from post-menopausal." (PMID 20553623, 2010).
lung carcinoma (4 papers, 2016 to 2025). "The expression of the proteins (p-STAT3, Bcl-2 and Survivin) showed no obvious changes when the phosphorylation of STAT3 was inhibited or IL11Rα were silenced in lung cancer cells." (PMID 27922075, 2016). "The effect of IL-11 on decreasing apoptosis rate could be neutralized in lung cancer cells with IL-11Rα knockdown (**p < 0.01)." (PMID 27922075, 2016). "However, the IL-11Rα expressions of two lung cancer cells were unchanged after treated by cisplatin." (PMID 27922075, 2016). "In this study, we revealed that ectopic expression of miR-19a or miR-19b-1 modulated the expression of IL-related genes (including IL1B, IL11RA, IL20RB, IL6 and IL32) and suppressed IL6 production in lung cancer and NPC cells." (PMID 32308549, 2020). "We examined IL‐11/IL‐11RA axis mediated changes in the lung TME using tobacco‐induced LUAD murine models, which are immunocompetent models that better approximate the clinical reality of smoking‐related lung cancer." (PMID 40673604, 2025). "In our study, we did not detect any change of the expression of IL-11Rα in lung cancer cells by cisplatin." (PMID 27922075, 2016). "Furthermore, lung cancer cells with IL-11Rα knockdown showed no response to IL-11." (PMID 27922075, 2016).
colon cancer (3 papers, 2019 to 2021). "Together, Il11ra expression in colonic epithelial cells increased along with tumor development, thereby enabling colon tumor cells to respond to IL-11 stimulation efficiently." (PMID 33863879, 2021). "Combined with miR-210-repressed hypoxia in obesity group, we inferred the inhibition of miR-210-hypoxia-IL11/IL11RA axis in obesity patients repressed the progression of colon cancer." (PMID 33197880, 2020). "The expression of GP130, IL-11, IL-11 receptor α (IL-11Rα), IL-6, IL-6 receptor (IL-6R) and STAT3 activation were examined by western blot in DLD-1, HCT-15, and HCT-116 colon cancer cell lines." (PMID 30736824, 2019). "After we identified the activation of GP130, IL-11, IL-11Rα and STAT3 expression in human colon cancer cells, we confirmed that the neutralized GP130 antibody could reduce the viability of human colon cancer cells." (PMID 30736824, 2019). "All three colon cancer cells highly expressed GP130, IL-11, IL-11Rα and p-STAT3." (PMID 30736824, 2019).
Gastric tumor (3 papers, 2010 to 2024). "Genetic deficiency for the ligand binding IL-11Rα subunit completely abrogates gastric tumour formation in gp130Y757F mice, and mono-allelic il11ra ablation delayed the onset and reduced overall gastric tumour burden." (PMID 20478049, 2010). "Gastric tumor formed in gp130Y757F/Y757F mice could be significantly abrogated by IL-11Rα knock-out and also by IL-11 signaling antagonist." (PMID 25929737, 2015).
glioblastoma (3 papers, 2023 to 2025). The most malignant astrocytic tumor (WHO grade IV). "Recently, we demonstrated the role of IL-11/IL-11Rα in promoting glioblastoma metabolic adaptation, leading to enhanced survival." (PMID 38248304, 2024). "In the present study, we define a critical role for the IL-11/IL-11Rα signalling axis in glioblastoma proliferation, epithelial to mesenchymal transition, and invasion." (PMID 38248304, 2024). "We then explore the biological effects of both overexpression and knockdown of IL-11Rα expression on glioblastoma proliferation, migration, and invasion in both two- and three-dimensional assays." (PMID 38248304, 2024). "Our current data also demonstrate a clear role in IL-11/IL-11Rα signalling promoting glioblastoma progression." (PMID 38248304, 2024). "Proteomic analysis of glioblastoma cell lines overexpressing IL-11Rα displayed a proteome that favoured enhanced proliferation and invasion." (PMID 38248304, 2024). "Nonetheless, our current discoveries identify IL-11Rα as a possible therapeutic target for treating glioblastoma." (PMID 38248304, 2024). "Our previously published data have shown that IL-11 expression correlates with glioblastoma patient survival and that IL-11Rα expression promotes enhanced survival of glioblastoma cells." (PMID 38248304, 2024). "Overall, our study identified that the IL-11/IL-11Rα pathway promotes glioblastoma cell proliferation, EMT, and invasion." (PMID 38248304, 2024). "Specifically, we explored a potential correlation between IL-11 and/or IL-11Rα expression in glioblastoma versus normal brain tissue and glioblastoma patient survival." (PMID 38248304, 2024). "We identified enhanced IL-11/IL-11Rα expression correlated with reduced overall survival in glioblastoma patients using TCGA datasets." (PMID 38248304, 2024). "We next performed proteomics analysis to determine a global differential protein expression between these IL-11Rα transfected glioblastoma cell lines and their parental counterparts." (PMID 38248304, 2024). "Our current data mining of the TCGA demonstrated that IL-11 and the IL-11Rα expression negatively correlated with glioblastoma patient survival." (PMID 38248304, 2024). "To further elucidate the role of IL-11 signalling, we next utilised two primary glioblastoma cell lines that we had previously stably transfected with IL-11Rα." (PMID 38248304, 2024). "Glioblastoma patient samples from our cohort and the TCGA also displayed a correlation between higher IL-11Rα and Bcl-2 gene expression." (PMID 36834778, 2023). "We identified enhanced IL-11/IL-11Rα expression correlated with reduced overall survival in glioblastoma patients." (PMID 36834778, 2023). "Here, we specifically demonstrate that IL-11Rα promotes the utilization of glioblastoma cells in glucose-deprived conditions to a glutamine-dependent metabolic mechanism subsequently providing protection from apoptosis mediated by glucose starvation." (PMID 36834778, 2023). "Investigation into IL-11Rα signaling, glutaminolysis and cell survival in regard to primary versus secondary glioblastoma is thus worth pursuing." (PMID 36834778, 2023). "Our data establish a novel IL-11Rα signalling–glutaminolysis metabolism axis where IL-11/IL-11Rα can promote glutamine metabolism and subsequently enhance survival of glioblastoma cells in low-glucose microenvironments." (PMID 36834778, 2023). "Nonetheless, in summary, our data suggest that IL-11Rα contributes to the ability of glioblastoma cells to metabolically adapt and subsequently survive in glucose-deprived conditions." (PMID 36834778, 2023). "We also found that the gene expression levels of IL-11 and IL-11Rα were increased in three of five primary glioblastoma cell lines and those patients in which the cell lines originated had decreased survival." (PMID 36834778, 2023).
glioblastoma (continued). "Overall, our study identified that the IL-11/IL-11Rα pathway promotes glioblastoma cell survival and enhances cell migration and invasion in environments of glucose starvation via glutaminolysis." (PMID 36834778, 2023). "As 96% of patients with primary glioblastoma contain wt IDH1 (as compared to only 27% of secondary glioblastoma), our study is only relevant to potential IL-11Rα-enhanced survival advantages in the primary glioblastoma context." (PMID 36834778, 2023). "In the present study, we define a critical role for the IL-11/IL-11Rα signalling axis in glioblastoma survival, proliferation and invasion when cells are starved of glucose." (PMID 36834778, 2023). "To further establish a model system to study the role of IL-11 signalling in glioblastoma cells, we stably transfected an IL-11Rα construct into the two cell lines (#20 and #28) with the lowest endogenous IL-11Rα expression." (PMID 36834778, 2023). "We demonstrate that under conditions of glucose starvation, IL-11Rα enables glioblastoma cells to utilise glutamine for survival, an adaption that protects glioblastoma cells from induced apoptosis." (PMID 36834778, 2023). "We propose that high IL-11/IL-11Rα expression leads to reduced apoptosis and subsequently greater glioblastoma progression and poorer patient survival rates potentially through enhanced glutaminolysis." (PMID 36834778, 2023). "Both IL-11 and IL-11Rα gene expression were detected at significantly higher levels in glioblastoma patient tissue compared to normal brain tissue, while the protein expression of IL-11Rα was found to be higher in glioblastoma tissue compared to normal tissue using the Human Protein Atlas database." (PMID 38248304, 2024). "As IL-11Rα could confer enhanced proliferation, we next examined if IL-11Rα could also promote glioblastoma cell migration and invasion." (PMID 38248304, 2024). "Here we show a clear role of IL-11/IL-11Rα signalling in glioblastoma progression." (PMID 38248304, 2024). "Furthermore, IL-11Rα expression in glioblastoma patient samples correlated with enhanced gene expression of the glutaminolysis pathway genes GLUD1, GSS and c-Myc." (PMID 36834778, 2023). "The contribution of IL-11/IL-11Rα signalling to glioblastoma progression is under-explored." (PMID 36834778, 2023). "As c-MYC has been shown to promote glutaminolysis in glioblastoma cells, we explored whether IL-11Rα expression correlated with c-MYC expression." (PMID 36834778, 2023). "Glioblastoma cell lines over-expressing IL-11Rα displayed greater survival, proliferation, migration and invasion in glucose-free conditions compared to their low-IL-11Rα-expressing counterparts, while knockdown of IL-11Rα reversed these pro-tumorigenic characteristics." (PMID 36834778, 2023). "Both IL-11 and Il-11Rα gene expression significantly correlated with reduced overall survival in glioblastoma patients, despite neither of these genes having a large alteration rate." (PMID 38248304, 2024). "In our present study, we connect these independent findings identifying that IL-11Rα expression correlates with both increased c-MYC and GLUD1 expression in glioblastoma patient tumor tissue and enhanced glutaminolysis leading to significantly greater survival in glucose-starved conditions." (PMID 36834778, 2023). "This suggests that IL-11Rα may be inducing c-MYC expression which then may allow for glutaminolysis and enhanced survival of glioblastoma cells in glucose-depleted conditions." (PMID 36834778, 2023). "Furthermore, high IL-11Rα expression also correlated with increased expression of GLUD1 and GSS, two key enzymes involved in glutaminolysis in both our glioblastoma cell lines and patient tumor tissue." (PMID 36834778, 2023). "However, a definitive pro-proliferative role of IL-11/IL-11Rα signalling has not been identified in the glioblastoma setting." (PMID 38248304, 2024).
glioblastoma (continued). "Indeed, glioblastoma patient tumor tissue with low IL-11Rα gene expression also displayed low levels of GLUD1 and GSS, while patient tumor tissue containing high IL-11Rα gene expression also contained significantly higher levels of GLUD1 and GSS gene expression." (PMID 36834778, 2023).
lung adenocarcinoma (3 papers, 2016 to 2025). A carcinoma that arises from the lung and is characterized by the presence of malignant glandular epithelial cells. "Our findings suggest that neutralising IL‐11RA mAb opens a new therapeutic strategy for lung adenocarcinoma patients and possibly for other types of inflammation‐related cancers." (PMID 40673604, 2025). "The statistical analysis demonstrated a correlation between IL-11Rα expression and responses to cisplatin-based chemotherapy in lung adenocarcinoma patients." (PMID 27922075, 2016). "The results showed that expression of IL-11Rα was also strongly correlated with chemoresistance of lung adenocarcinoma." (PMID 27922075, 2016). "In lung adenocarcinoma, studies using transcriptomic analysis and Mendelian randomization have revealed that IL11RA expression is downregulated in tumor tissues and exhibits a significant negative correlation with lung adenocarcinoma risk, suggesting a potential tumor suppressor role." (PMID 40755754, 2025). "This study confirmed a negative association between IL11RA expression and bladder cancer risk, consistent with previous findings in lung adenocarcinoma." (PMID 40755754, 2025). "The effect could be abrogated by suppressing STAT3 phosphorylation or silencing IL-11Rα in lung adenocarcinoma cells." (PMID 27922075, 2016). "The expression of IL-11Rα in lung adenocarcinoma tissue was stained by immunohistochemistry." (PMID 27922075, 2016). "Furthermore, this effect could be neutralized by silencing the expression of IL-11Rα in lung adenocarcinoma cells (A549 and H1975)." (PMID 27922075, 2016). "And the effect could be neutralized by IL11Rα-knockdown in lung adenocarcinoma cells." (PMID 27922075, 2016). "IL-11Rα expression in lung adenocarcinoma cells and CAF were examined by immunofluorescence and IL-11Rα mainly expressed in cell membrane and cytoplasm of the cells." (PMID 27922075, 2016).
rheumatoid arthritis (3 papers, 2018 to 2023). A chronic, systemic autoimmune disorder characterized by inflammation in the synovial membranes and articular surfaces. "Other studies have shown that in rheumatoid arthritis (RA), IL-11 combined with IL-11RA in the endothelial cell directly activates RA angiogenesis." (PMID 37304948, 2023). "One study showed that IL-11 and IL-11Rα are co-expressed in rheumatoid arthritis synovitis fluid fibroblasts and endothelial cells and thus interconnect the function of these two cell types, whereas macrophages are not IL-11 responder cells because of no IL-11Rα expression." (PMID 30197757, 2018).
colorectal adenocarcinoma (2 papers, 2010 to 2024). The most common type of colorectal carcinoma. "Similarly, the density of IL-11Rα was higher in the more invasive regions of colorectal adenocarcinoma." (PMID 38248304, 2024). "Similarly, IL11 and IL11Rα protein are highly expressed in human colorectal adenocarcinoma and IL11Rα levels correlate with clinicopathological factors." (PMID 20553623, 2010).
COVID-19 (2 papers, 2021 to 2023). A disease caused by infection with severe acute respiratory syndrome coronavirus 2. "The routine COVID-19 serum markers (ferritin and procalcitonin), along with our retrieved novel marker, the IL11RA protein, have been analyzed using the ROC curves of the investigated groups." (PMID 34831321, 2021). "In the same context, the pattern of increases in ferritin, procalcitonin and IL11RA was highly discriminative between mild and severe cases of COVID-19, compared to healthy controls." (PMID 34831321, 2021). "The expression of the IL11RA molecular network was assessed via the fold-change (RQ) values in the different investigated groups (mild COVID-19, severe COVID-19 and healthy control) in order to confirm the retrieved bioinformatics data." (PMID 34831321, 2021). "We finally concluded that the IL11RA molecular network could be used for predicting the severity of COVID-19 alone or in combination with the existing biomarkers procalcitonin and ferritin." (PMID 34831321, 2021). "Interestingly, the expression pattern of the IL11RA molecular network was discriminative between COVID-19-positive patients and healthy controls, and between mild and severe COVID-19 compared to healthy controls." (PMID 34831321, 2021). "IL11RA mRNA and LncRNA RP11-773H22.4 were overexpressed by 100-fold and 6-fold in mild COVID-19 cases compared to the healthy control group, and by 9-fold and 72-fold in severe COVID-19 cases compared to mild COVID-19 cases, respectively." (PMID 34831321, 2021). "As expected, IL11RA mRNA and LncRNA RP11-773H22.4 expressions were upregulated, and hsa-miR-4257 was downregulated in the COVID-19 group compared to the healthy control group (p < 0.000)." (PMID 34831321, 2021). "Moreover, by assessing the serum levels of ferritin, procalcitonin (ENSGOOOOO110680) and IL11RA proteins (ENST00000441545.7) in the studied groups, we found significant increases in the three proteins in the COVID-19 group compared to the healthy control group (p < 0.000)." (PMID 34831321, 2021). "Moreover, the best cutoff values were 15.95 for IL11RA mRNA (AUC = 0.803) and 40.5 for LncRNA RP11-773H22.4 (AUC = 0.777), and these could be used to differentiate mild from severe COVID-19 cases, with sensitivities of 73.2% and 78% and specificity values of 76% and 71%, respectively." (PMID 34831321, 2021).
melanoma (2 papers, 2009 to 2023). A malignant, usually aggressive tumor composed of atypical, neoplastic melanocytes. "According to our qRT-PCR data, the relative expression level of the IL11RA gene was significantly higher in primary melanoma tissues with liver metastasis compared to primary melanoma without metastasis." (PMID 37240247, 2023). "It is very important to emphasize that we detected significantly higher IL11RA gene expression in primary melanoma tissues with liver metastasis as well, compared to those without metastasis." (PMID 37240247, 2023). "The overexpression of the IL11RA gene in association with melanoma liver metastasis has not been described yet, but it is important to note that we found significantly higher mRNA levels in the selected invasive melanoma cells after HHSEC-CM treatment." (PMID 37240247, 2023). "Based on our data, overexpression of the IL11RA gene might have a key role in the formation of organ-specific metastasis to the liver induced by primary melanoma cells." (PMID 37240247, 2023). "Furthermore, we assume that overexpression of the IL11RA gene may play a key role in organ-specific metastasis of primary melanoma cells to the liver." (PMID 37240247, 2023). "We had the opportunity to compare the IL11RA expression levels of primary melanoma tissues with and without liver metastasis; similar to our model experiments, we found a significant increase in the IL11RA gene expression in primary melanoma tissues with liver metastasis." (PMID 37240247, 2023).
neuroblastoma (2 papers, 2024 to 2025). Neuroblastoma (NB) is the most common solid, extracranial childhood tumor. "Therefore, IL11RA may promote differentiation in neuroblastoma." (PMID 38398114, 2024). "Given the numerous pathways activated by IL11 signalling (the ligand of IL11RA), including JAK-STAT, Ras-MAPK, PI3K-AKT, and NF-κB, the complexity of signalling and interaction could mean tissue- and pathway-specificity for the effect of IL11RA upregulation on neuroblastoma." (PMID 38398114, 2024).
autoimmune disease (1 paper, 2024). A disorder resulting from loss of function or tissue destruction of an organ or multiple organs, arising from humoral or cellular immune responses of the individual to their own tissue constituents. "We combined computational and histological approaches to validate the expression status of IL11 and IL11Rα in human fibrotic and additional autoimmune diseases." (PMID 38455057, 2024).